GAS5 (growth arrest specific 5)
Diseases named in the same sentence as GAS5 in open-access papers (continued):
Sharing a sentence is not in itself a finding about the gene and the disease.
type 2 diabetes (16 papers, 2017 to 2025). "This agent binds lncRNA GAS5 with high affinity in adipose-derived stem cells, hinders its interaction with UPF1, and prevents lncRNA GAS5 degradation, thereby alleviating type 2 diabetes." (PMID 40563948, 2025). "We have demonstrated that GAS5 expression is significantly lower in type 2 diabetes and further demonstrated that GAS5 regulates the expression of insulin receptor." (PMID 35336800, 2022). "GAS5 lncRNA is being currently studied at a pre‐clinical level as a potential biomarker for type 2 diabetes (T2D) and coronary artery disease (CAD)." (PMID 32100288, 2020). "One completely novel molecular mechanism for GAS5 function has recently been suggested from its role in type 2 diabetes mellitus (T2D)." (PMID 31533355, 2019). "In support of our findings, increased expression of GAS5 and lncRNA ENST00000550337.1 was reported in type 2 diabetes even with high diagnostic claim and biomarker value." (PMID 30139387, 2018). "The other relevant gene was GAS5, an lncRNA gene that was investigated for being a biomarker for type 2 diabetes, which might be also involved in MDD progression through mRNA regulation." (PMID 39457495, 2024). "For instance, GAS5 lncRNA may serve as a possible biomarker for type 2 diabetes (T2DM) and coronary artery disease (CAD)." (PMID 33804455, 2021). "Additionally, the circulating levels of lncRNA growth-arrest-specific 5 (GAS5) have been found to be reduced both in diabetic patients as well as in a type 2 diabetic mouse model, suggesting an involvement of this lncRNA in the pathogenesis of this disease." (PMID 34681797, 2021). "Our results in adipose tissue indicate that inhibition of release of PKCδI_C further reduces Gas5, while increasing the levels of Meg3 in DIO mice, suggesting a PKCδI-dependent pathway promoting the onset of type 2 diabetes in obesity." (PMID 39596898, 2024). "Compared to control subjects, expression profiling of lncRNAs in PBMCs from type 2 diabetes patients showed significantly (p < 0.05) increased levels of HOTAIR, MEG3, LET, MALAT1, MIAT, CDKN2BAS1/ANRIL, XIST, PANDA, GAS5, Linc-p21, ENST00000550337.1, PLUTO, and NBR2." (PMID 30139387, 2018). "Compared to control subjects, expression levels of lncRNAs in PBMCs from type 2 diabetes patients showed significantly (p < 0.05) increased levels of HOTAIR, MEG3, LET, MALAT1, MIAT, CDKN2BAS1/ANRIL, XIST, PANDA, GAS5, Linc-p21, ENST00000550337.1, PLUTO, and NBR2." (PMID 30139387, 2018). "However, GAS5 expression wassignificantly higher in obese subjects with type 2 diabetes(T2D) compared to obese subjects without T2D." (PMID 40567589, 2025). "Afteradjusting for type 2 diabetes diagnosis, GAS5 expression levelswere significantly higher (~3 fold of change of the mean)( p = 0.03) in obese subjects with T2D compared to obesepatients without T2D." (PMID 40567589, 2025). "Similarly, of the tested lncRNAs, only GAS5 showed significantly higher expression levels in obese patients with type 2 diabetes (T2D) (n = 10) compared to obese patients without T2D (n = 60)." (PMID 40567589, 2025).
systemic lupus erythematosus (15 papers, 2017 to 2025). An autoimmune multi-organ disease typically associated with vasculopathy and autoantibody production. "As for lupus, in 2006, six SNPs in the promoter region of Growth arrest-specific 5 (GAS5) had been identified to cause 11-fold down-regulation of the lncRNA expression and correlated with nephritis susceptibility in spontaneous lupus nephritis mouse model BXSB strain." (PMID 30619325, 2018). "Circulating or cell-associated ncRNA signatures, particularly elevated miR-155, miR-21, and diminished GAS5 or miR-146a, have already shown promise as biomarkers that track disease activity across lupus, RA, and MS cohorts." (PMID 41376628, 2025). "Low GAS5 levels were correlated with higher T cell activation status and IL-2 production in lupus." (PMID 41376628, 2025). "Thus, in lupus T cells, GAS5 downregulation leads to unchecked miR-92a activity, which in turn downregulates E4BP4, relieving repression on activation-induced genes." (PMID 41376628, 2025). "The co-expression analysis showed that GAS5, lnc0640, and lnc5150 might participate in the lupus pathogenesis via the signaling pathway." (PMID 33291347, 2020). "Importantly, one case-control study demonstrated a functional link: overexpressing GAS5 in lupus patient T cells in vitro (using a plasmid or viral vector) inhibited T cell activation and even reduced the “self-reactivity” of those lupus T cells (measured by autoreactive T cell responses)." (PMID 41376628, 2025).
autoimmune disease (14 papers, 2013 to 2023). A disorder resulting from loss of function or tissue destruction of an organ or multiple organs, arising from humoral or cellular immune responses of the individual to their own tissue constituents. "Aberrant expressions of IFNG-AS1 and GAS5 are directly linked to numerous autoimmune disorders but their levels in childhood ITP are still obscure." (PMID 36310591, 2022). "Abnormal IFNG-AS1 and GAS5 expression levels have been linked to a number of autoimmune disorders, implying that these genes may play a role in the pathogenesis of autoimmunity and could represent new targets of therapy." (PMID 36310591, 2022). "However, whether the lncRNA GAS5 over-expression is really involved in the pathogenesis of some of the typical features of KS patients (particularly in inflammatory and autoimmune diseases, atherogenesis and germ cell loss) needs to be further investigated." (PMID 30612561, 2019). "LncRNA growth arrest‐specific transcript 5 (GAS5) has been proven to be involved in autoimmune diseases." (PMID 34936242, 2022). "All this is consistent with the possible involvement of lncRNA GAS5 in the pathogenesis of inflammatory and autoimmune diseases, more frequently occurring in patients with DS." (PMID 32624686, 2020). "GAS5 plays a widespread role in different diseases, including cancers, inflammation-related diseases, obesity and autoimmune diseases." (PMID 33195407, 2020). "LncRNA GAS5 has been reported to play a role in inflammatory and autoimmune disorders, apoptosis and glucocorticoid (GC) actions 8,12." (PMID 32624686, 2020). "LncRNA GAS5 down-expression may play a role in the development of some typical features of the patients with DS and, particularly, in inflammatory and autoimmune diseases." (PMID 32624686, 2020). "In fact, one of the mechanisms by which lncRNA GAS5 could be involved in the development of autoimmune disorders may be its influence on the glucocorticoid receptor (GCR) function." (PMID 32624686, 2020). "Furthermore, recent evidence suggests that lncRNA GAS5 plays a role in autoimmune disorders 8, widely recognized as important DS comorbidities." (PMID 32624686, 2020). "GAS5 interacts with the DNA binding domain of glucocorticoid receptors (GRs), and preventing GRs from connecting with DNA, preventing glucocorticoid activity which is a powerful immunosuppressive and hence contributes to the development of autoimmune disorders." (PMID 36310591, 2022). "Similarly, rs6790 was reported to play inhibitory functions of GAS5 on the transcriptional activity of GR in autoimmune disease, GAS5 knock-down could attenuate the progression of experimental autoimmune encephalomyelitis (EAE) and promote remyelination." (PMID 31905737, 2019). "Furthermore, this research brings us to the knowledge that GAS5 may contribute to a new molecular regulation of autoimmune diseases and may provide insights into the identification of lncRNAs as biomarkers for disease activity and potential therapeutic targets." (PMID 37198993, 2023).
diabetic nephropathy (14 papers, 2019 to 2025). "The GAS5/miR-452-5p axis has also been demonstrated to have a prominent role in reducing the extent of diabetic nephropathy-related inflammation, oxidative stress, and pyroptosis in renal tubular cells." (PMID 39941145, 2025). "In the kidney tissues of type 2 DM with diabetic nephropathy, GAS5 is also downregulated compared with that in patients without diabetic nephropathy." (PMID 35207562, 2022). "In the diabetic nephropathy model, positive feedback on the loop of C/EBPb/GAS5/miR-18a-5p was activated to reduce mitochondrial reactive oxygen species in HK-2 cells." (PMID 35619068, 2022). "LncRNA GAS5 alleviated fibrosis via inhibition of MMP9 by recruitment of EZH2 in diabetic nephropathy." (PMID 36313695, 2022). "MiR-452-5p and miR-221-3p are two valid targets of GAS5 in renal tubular cells and mesangial cells, respectively, and both of them are involved in diabetic nephropathy." (PMID 33195407, 2020). "It has been reported that GAS5 targets to miR-452-5p and miR-221-3p in renal tubular cells and mesangial cells, which are involved in diabetic nephropathy." (PMID 33195407, 2020). "Recent research revealed that miR-221 is protected from sponging via lncRNA growth arrest-specific 5 (GAS5) in diabetic nephropathy and thus leading to SIRT1 decrease." (PMID 32962281, 2020). "This protective function is further exemplified by the ability of GAS5 to reduce renal fibrosis in diabetic nephropathy (DN) through sponging miR-221, which elevates SIRT1 expression, highlighting its potential role in mitigating fibrosis and promoting cellular homeostasis in the kidney." (PMID 39941145, 2025). "In diabetic nephropathy, GAS5 expression is low and MMP9 expression is high." (PMID 34712322, 2021). "In diabetic nephropathy studies show that GAS5 is reduced in renal tissue and in high-glucose-challenged tubular cells, and that restoring GAS5 attenuates oxidative stress, pyroptosis, and profibrotic signaling through miRNA axes such as GAS5/miR-452-5p and GAS5/miR-221." (PMID 41303683, 2025). "Given that SIRT1 is a protein deacetylase that helps to antagonize oxidative stress in various disease conditions, including diabetes, it is reasonable to postulate that upregulation of GAS5 may downregulate the increased oxidative stress in diabetic nephropathy." (PMID 35207562, 2022). "LncRNA GAS5 suppressed fibrosis and cell proliferation through attenuating miR-221 and upregulating SIRT1 expression in diabetic nephropathy." (PMID 36313695, 2022). "Long noncoding RNA GAS5 was proved to limit cell proliferation and fibrosis by sponging miR-221 and regulating SIRT1 levels in diabetic nephropathy." (PMID 32528555, 2020). "Even though two molecules, lncRNA GAS5 and miR-21, have been studied separately in the context of high glucose and DN, their regulatory networks in diabetic nephropathy have not been studied." (PMID 37821982, 2023). "However, other studies demonstrate that the expression of GAS5 in kidney tissues of STZ-induced diabetic nephropathy rats is decreased, which may alleviate renal fibrosis in diabetic nephropathy." (PMID 35207562, 2022). "Further studies showed that GAS5 downregulated matrix metalloproteinase 9 (MMP9) expression by recruiting EZH2 to the MMP9 promoter region, while lentivirus-mediated MMP9 silencing reduced RIF and suppressed the inflammatory response in the kidneys of rats with diabetic nephropathy." (PMID 34712322, 2021).
lung adenocarcinoma (14 papers, 2015 to 2025). A carcinoma that arises from the lung and is characterized by the presence of malignant glandular epithelial cells. "The results showed that GAS5 is downregulated in lung adenocarcinoma tissues, and lower expression levels are associated with larger tumor sizes, poor differentiation, and advanced pathological stages." (PMID 38200584, 2024). "On the other side, the GAS5 and its SNP is another genetic risk factor for cardiovascular disease and various malignancies including the lung adenocarcinoma." (PMID 36011604, 2022). "GAS5 had several mapped CpGs associated with smoking in adult blood, newborn blood, and in lung adenocarcinoma (including the genome-wide significant cg16290996)." (PMID 30872662, 2019). "In conclusion, the presence of the GAS5 SNP rs145204276 variant could lead to advanced clinicopathological characteristics of lung adenocarcinoma under the presence of the EGFR wild type." (PMID 36011604, 2022). "Further large-scale prospective studies to evaluate whether the GAS5 SNP rs145204276 and other variants would affect the therapeutic outcome in lung adenocarcinoma with wild-type wild type are mandatory." (PMID 36011604, 2022). "In our study, the GAS5 SNP rs145204276 Ins/Del + Del/Del contributed to worse tumor condition concerning the tumor stage, tumor T status and lymph node status in lung adenocarcinoma patients with EGFR wild type." (PMID 36011604, 2022). "This is a relatively new finding that the SNP of GAS5 can grossly affect the clinicopathological characteristics of lung adenocarcinoma with wild-type EGFR." (PMID 36011604, 2022). "A further study is needed to explore the effectiveness of a combination therapy that would include GAS5 in lung adenocarcinoma, particularly in patients with EGFR-TKI resistance." (PMID 31847392, 2019). "Levels of GAS5 were downregulated in the EGFR TKI resistant lung adenocarcinoma cell line A549 compared to sensitive cell lines." (PMID 29701689, 2018). "Collectively, our study explores the validity of using GAS5 as a new treatment approach in lung adenocarcinoma." (PMID 25925741, 2015). "To investigate the expression of growth arrest-specific 5 (GAS5) in lung adenocarcinoma, we performed real-time reverse-transcriptase polymerase chain reaction." (PMID 25925741, 2015). "In the present study, we found that GAS5 expression was significantly downregulated in lung adenocarcinoma tissues compared to the adjacent normal lung tissue, which is of clinical significance." (PMID 25925741, 2015). "The potential relationship between GAS5 levels in tumors and the clinicopathological features of lung adenocarcinoma patients were investigated." (PMID 25925741, 2015). "Our results also showed that GAS5 overexpression reversed the gefitinib resistance of the human lung adenocarcinoma A549 cell line." (PMID 25925741, 2015). "Because of the significance of LncRNAs in biological processes, we examined the impact of GAS5 overexpression on gefitinib resistance in the resistant lung adenocarcinoma cell line." (PMID 25925741, 2015). "We found that GAS5 was expressed at a comparatively low level in the four lung adenocarcinoma cell lines compared with the human bronchial epithelial (HBE) cell line." (PMID 25925741, 2015). "In this study, we demonstrated, for the first time, that GAS5 exerts a tumor suppressive function by regulating IGF-1R expression in lung adenocarcinoma." (PMID 25925741, 2015). "Our results revealed that GAS5 is a promising molecule that is capable of overcoming the resistance to EGFR inhibitors in lung adenocarcinoma." (PMID 25925741, 2015). "Still, whether the length of cigarette smoking period would interact with GAS5 SNP rs145204276 and alter the clinicopathological characteristics of lung adenocarcinoma needs further validation." (PMID 36011604, 2022).
lung adenocarcinoma (continued). "The present study examined the relationship between the GAS5 single-nucleotide polymorphisms (SNPs; rs145204276 Ins/Del, rs55829688 T/C) and the clinicopathological factors in 539 lung adenocarcinoma patients with or without EGFR mutations." (PMID 36011604, 2022). "In conclusion, these data indicate that the GAS5 SNP rs145204276 variant may help predict tumor stage, lymph node metastasis and distal metastases in patients with EGFR wild type lung adenocarcinoma." (PMID 36011604, 2022). "However, there are scant studies that discuss the SNP of GAS5 and its correlation to the clinical features of lung adenocarcinoma." (PMID 36011604, 2022). "On the other hand, there may not be strong relationships between the distribution frequencies of GAS5 SNP rs55829688 and the clinicopathologic characteristics of lung adenocarcinoma in all EGFR genotypes (all p > 0.05)." (PMID 36011604, 2022). "In more details, the GAS5 SNP rs145204276 Ins/Del + Del/Del causes a higher tumor stage and leads to distal metastases in non-smokers with lung adenocarcinoma and wild-type EGFR." (PMID 36011604, 2022). "Consequently, the purpose of the current study was to evaluate the effect of GAS5 SNP plus EGFR phenotypes on the clinical manifestations of lung adenocarcinoma." (PMID 36011604, 2022). "This particular study recognised the effect of GAS5 in enhancing apoptosis due to gefitinib activity within innate EGFR tyrosine-kinase inhibitor (TKI) resistant lung adenocarcinomas (A549 cell line), through the gene regulating role of GAS5 on insulin-like growth factor 1 receptor (IGF-1R)." (PMID 28273813, 2017). "Taken together, our results indicate that GAS5 plays an important role in lung adenocarcinoma development and could be a potential therapeutic target for lung adenocarcinoma patients." (PMID 25925741, 2015). "The IGF-1R (insulin-like growth factor 1 receptor) protein level, which has been associated with resistance to EGFR-TKIs, was also analyzed to explore the potential mechanisms behind the effects of the GAS5/gefitinib combination on gefitinib-resistant lung adenocarcinoma cells." (PMID 25925741, 2015). "Consequently, the GAS5 genotype analyses in patients with lung adenocarcinoma and EGFR wild type may be suggested to find advanced tumor condition." (PMID 36011604, 2022). "Also, because the SNPs of other gene would interact with EGFR genotype and affect the characters of lung adenocarcinoma, a similar action may occur between GAS5 SNPs and EGFR which need additional evaluation." (PMID 36011604, 2022). "Consequently, the genotypes of these two genetic factors, the EGFR and GAS5, may interact and alter the clinical course of lung adenocarcinoma." (PMID 36011604, 2022). "GAS5 was found to be downregulated in EGFR-TKI resistant lung adenocarcinoma cell line A549 compared to sensitive cell lines and GAS5 overexpression could greatly sensitize A549 cells to gefitinib and GAS5 overexpression in A549 xenograft mouse models potentiated gefitinib treatment." (PMID 28430163, 2017). "Collectively, our results indicated that GAS5 LncRNA may represent a potential biomarker for the diagnosis of lung adenocarcinoma and that GAS5 might play a novel role in the development of the resistance to gefitinib, which could be reversed by overexpressing GAS5." (PMID 25925741, 2015). "Our work suggests that GAS5 LncRNA expression may represent a valuable marker for diagnosis and outcome predictions in patients with lung adenocarcinoma and that increased GAS5 expression may overcome the resistance to EGFR-TKIs in resistant lung adenocarcinoma, both in vitro and in vivo." (PMID 25925741, 2015). "Therefore, we hypothesized that GAS5 may also mediate IGF-1R function to enhance the sensitivity to EGFR-TKIs in lung adenocarcinoma." (PMID 25925741, 2015). "The overexpression of GAS5 varied inversely with the expression of EGFR pathway and IGF-1R proteins in lung adenocarcinoma tissues." (PMID 30853980, 2019).